LINC01419 (long independently transcribed non-coding RNA 1419)
Synonyms: TCONS_00014497; PRLH1; LVCAT7
Gene: Long non-coding RNA gene on chromosome 8 (83,403,739 to 83,408,900, forward strand). Ensembl gene ENSG00000253898.
Diseases named in the same sentence as LINC01419 in open-access papers:
LINC01419 is named in the same sentence as 9 diseases in open-access papers, as found by Europe PMC text mining. Sharing a sentence is not in itself a finding about the gene and the disease. The quoted sentences say what the papers report.
colon cancer (1 paper, 2018). "We noted that 11 lncRNAs, SCARNA10, RPPH1, LINC01419, ERVH48-1, RMRP,CH507-513H4.3, MIR205HG, CH507-513H4.6, LINC00400, RP11-774D14.1 and AC006050.2, were also differentially expressed in colon cancer samples compared with the normal samples." (PMID 29420609, 2018).
esophageal squamous cell carcinoma (1 paper, 2020). Esophageal squamous cell carcinoma (ESCC) is a type of esophageal carcinoma (EC) that can affect any part of the esophagus, but is usually located in the upper or middle third. "Long intergenic non-protein coding RNA 1419 (LINC01419) has been demonstrated as an oncogene in lung adenocarcinoma, esophageal squamous cell carcinoma and gastric cancer." (PMID 32390762, 2020).
lung adenocarcinoma (1 paper, 2022). A carcinoma that arises from the lung and is characterized by the presence of malignant glandular epithelial cells. "LINC01419 is found to facilitate proliferation and metastasis of lung adenocarcinoma (LUAD) cells, but there is a great deal of uncertainty about how LINC01419 works on LUAD cell stemness." (PMID 36050791, 2022).
lung carcinoma (1 paper, 2022). "According to these findings, the potential of LINC01419 to be the target for LUAD treatment is hence determined, which also adds more possibility to the enrichment of therapeutic strategies for lung cancer stem cells." (PMID 36050791, 2022).
osteosarcoma (1 paper, 2021). A usually aggressive malignant bone-forming mesenchymal neoplasm, predominantly affecting adolescents and young adults. "LncRNA LINC01419 was noted to regulate PDRG1/miR-519a-3p axis to induced osteosarcoma cell progression." (PMID 34102610, 2021).
tumor (7 papers, 2015 to 2024). "The results demonstrated that DCA effectively suppressed the tumour growth triggered by overexpression of LINC01419, further indicating that PDK1 is the major downstream effector of LINC0419." (PMID 39625183, 2024). "Consistently, overexpression of YBX1 countered the inhibitory effect of LINC01419 knockdown on tumour growth in vivo." (PMID 39625183, 2024). "Collectively, these findings suggest that glucose‐induced LINC01419 is associated with poor prognosis in HCC patients and promotes the growth and metastasis of HCC tumours." (PMID 39625183, 2024). "In our research, the silencing of LINC01419 was accompanied by an increase in γ-H2AX, implying increased DNA damage, suggesting that the upregulated LINC01419 in HCC promotes tumor progression by maintaining genomic stability." (PMID 35903292, 2022). "The downregulation of LINC01419 suppresses tumor growth and promotes autophagy through the inactivation of the PI3K/Akt1/mTOR pathway in GC (Wang L.-L." (PMID 34805143, 2021). "Downregulation of LINC01419 suppresses tumor growth and promotes autophagy through inactivation of the PI3K/Akt1/mTOR pathway in GC." (PMID 34805143, 2021). "In this study, we probed into the function of LINC01419 in OS and found the high expression trend and tumor-facilitating role of LINC01419 in OS, providing a new thought for future OS treatment." (PMID 32390762, 2020). "In vivo imaging revealed that the knockdown of LINC01419 strongly suppressed in situ tumour growth." (PMID 39625183, 2024). "In addition, tumor sphere-forming assay showed that LINC01419 overexpression significantly promoted LUAD stem cell sphere-forming, while LINC01419 silencing expression inhibited LUAD stem cell sphere-forming." (PMID 36050791, 2022). "Thus, our findings suggest that LINC01419 and AK021443 could regulate cell cycle activity and thereby promote tumor growth." (PMID 26540467, 2015).
cancer (5 papers, 2020 to 2024). A tumor composed of atypical neoplastic, often pleomorphic cells that invade other tissues. "To summarize, our findings demonstrate a cancer-promoting role of LINC01419 in LUAD." (PMID 36050791, 2022). "LINC01419 is a non-coding RNA longer than 200 bp, and a growing body of studies have shown that LINC01419 is up-regulated in LUAD to play a cancer-promoting role." (PMID 36050791, 2022). "AFAP1-AS1 promotes the development of various cancers and indicates a poor prognosis for HCC, while LINC01419 promotes cell proliferation and metastasis in HCC." (PMID 35629368, 2022). "It has been shown that LINC01419 is up-regulated in LUAD and plays a cancer-promoting role." (PMID 36050791, 2022). "Recently, long intergenic non-protein coding RNA 1419 (LINC01419) has been reported to function as an oncogene in several cancers." (PMID 32390762, 2020). "In addition, the expression level of LINC01419 in LUAD cell lines was detected by qRT-PCR, and LINC01419 was significantly up-regulated compared with normal lung cells, indicating that LINC01419 may play a cancer-promoting role in LUAD." (PMID 36050791, 2022).
LINC01419 also shares sentences with these, for which no sentence is quoted: hepatocellular carcinoma (4 papers); gastric cancer (1).